FABP4 (fatty acid binding protein 4)
Diseases named in the same sentence as FABP4 in open-access papers (continued):
Sharing a sentence is not in itself a finding about the gene and the disease.
ovarian carcinoma (continued). "In addition to in vitro experiments, knock out of FABP4 in ovarian cancer cells caused decreased tumor burden and number of metastatic nodules in intraperitoneal OC mouse models, convincingly establishing the link between lipid metabolism and the metastatic phenotype." (PMID 31769430, 2019). "The expression level of FABP4 can serve as an independent prognostic indicator for cancers such as breast and ovarian cancer." (PMID 40717587, 2025). "Ovarian cancer cells take up fatty acids released by adipocytes through FABP4, promoting their survival and metastasis." (PMID 40717587, 2025). "Regarding therapy resistance, FABP4 enhances mitochondrial β-oxidation to reduce apoptosis in ovarian cancer, and FABP5 promotes chemoresistance in HCC via the HIF-1α pathway." (PMID 40717587, 2025). "FABP4 is overexpressed in ovarian metastatic carcinoma of the greater omentum, and the inhibition of FABP4 results in limited ovarian cancer metastasis." (PMID 39984452, 2025). "For example, Orlistat inhibits FABP1 activity to enhance immunotherapy efficacy in HCC, BMS309403 targets FABP4 to inhibit ovarian cancer metastasis and enhance chemosensitivity, and SBFI-26 induces ferroptosis in liver cancer cells by inhibiting FABP5." (PMID 40717587, 2025). "FABP4 knockdown down-regulated the signature genes involved in ovarian cancer and even decreased the clonogenic survival rate." (PMID 41065381, 2025). "Hypoxia increases lipid uptake and FABP4 levels in ovarian cancer cells by downregulating the FABP4 inhibitory microRNA miR-409-3p." (PMID 39284708, 2024). "In ovarian cancer cells, enhanced expression of FABP4 induced by adipocytes not only promotes metastasis but also mediates resistance to carboplatin." (PMID 39610918, 2024). "In ovarian cancer, fatty acid binding protein 4 (FABP4) secreted by co-cultured adipocytes critically modulates lipid responses in ovarian cancer cells." (PMID 38540217, 2024). "It has been reported that ovarian cancer cells modify their lipid metabolism by upregulating fatty acid-binding protein 4 (FABP4) in the adipocyte-cancer cell interface at omental metastases." (PMID 39802952, 2024). "For instance, adipocytes fuel fatty acids for ovarian cancer to boost metastatic tumor cell growth at distant sites via elevated fatty acid-binding protein 4 (FABP4)." (PMID 38216787, 2024). "In ovarian cancer, adipocytes produce fatty acids, which are taken up by FABP4-expressing cancer cells and oxidized into ATP." (PMID 39284708, 2024). "Adipocyte-induced FABP4 expression in ovarian cancer cells promotes metastasis and mediates resistance to carboplatin." (PMID 36890467, 2023). "In the context of ovarian cancer, FABP4 plays a central role in regulating adipocyte-induced lipid metabolism in cancer cells." (PMID 37681030, 2023). "For example, IL‐17A, a vital proinflammatory cytokine, has been found to upregulate FABP4 to realize more fatty acid uptake through the IL‐17A/IL‐17RA/p‐STAT3/FABP4 axis to help ovarian cancer cell growth and metastasis in an adipose‐rich environment." (PMID 37605299, 2023). "FABP4 expression is strongly exhibited at the interface between adipocyte and ovarian cancer cells, enhancing lipid availability in cancer cells and promoting rapid tumor growth and metastasis." (PMID 38060103, 2023). "In a co-culture model involving ovarian cancer cells and adipocytes, treatment with an FABP4 inhibitor attenuated lipid accumulation in the cancer cells, reducing migration and invasion of cancer cells facilitated by adipocytes." (PMID 38060103, 2023). "Upregulation of fatty acid-binding protein 4 (FABP4), also known as adipocyte protein 2, has been found in omental metastases of serous ovarian cancer compared with primary ovarian cancers." (PMID 36498537, 2022). "Human ovarian cancer cells preferentially metastasise and home to the omentum, where they express high levels of FABP4 to assist fatty acid transfer from local adipocytes, providing a proliferative advantage." (PMID 34983949, 2022).
ovarian carcinoma (continued). "The FABP4 upregulation can also be induced by cytokine IL-17A secreted by IL-17A-producing cells via p-STAT3 signaling in the metastatic process of ovarian cancer to omentum." (PMID 35899119, 2022). "Co-culturing of SKOV3ip1 human ovarian cancer cells with human omental biopsies identified FABP4 as one of the 16 significantly altered proteins in the cancer cells." (PMID 35565396, 2022). "One study revealed that FABP4 is a pivotal regulator of metastasis in ovarian cancer cells through miR-409-3p modulation." (PMID 36114448, 2022). "Human recombinant IL-17A induces fatty acid uptake by upregulating FABP4 expression in OvCa cells and consequently contributes to the progression and metastasis of ovarian cancer cells." (PMID 35216285, 2022). "FABP4 substantially increases the metastatic potential of ovarian cancer cells by altering the levels of 5-hydroxymethylcytosine in the DNA and the expression of key genes involved in the metastasis-related and metabolic pathways." (PMID 35899119, 2022). "FABP4 is found in stromal cells and can trigger cancer growth by supplying energy to cancer cells or increasing angiogenesis in ovarian cancer cells." (PMID 36114448, 2022). "Specifically, IL-17A activated STAT3 phosphorylation to promote FABP4 expression, thereby increasing ovarian cancer cell proliferation." (PMID 35216285, 2022). "For example, studies using ovarian cancer cells indicate increased FABP4 expression in tumor cells located adjacent to adipocytes." (PMID 36358315, 2022). "FABP4 is involved in the regulation of metastasis-related pathways and affects the metabolic pathways of ovarian cancer cells, which can significantly increase the metastatic potential of cancer cells." (PMID 36532833, 2022). "In ovarian cancer, FABP4 is related to the supply of FAs from the surrounding adipocytes, and it is also a key determinant of the metastatic potential." (PMID 36613455, 2022). "That study established a metastasis-promoting role for lipid accumulation, FABP4 expression and lipid metabolism in ovarian cancer." (PMID 34983949, 2022). "Overall, therapeutic strategies specifically targeting lipid metabolism and transport such as FABP4 inhibitors in ovarian cancer are full of hope." (PMID 36341388, 2022). "Harjes investigated the role of FABP4 and found that FABP4 knockdown inhibited growth, metastasis, and angiogenesis of ovarian cancer in vitro and in vivo." (PMID 36114448, 2022). "It has been found that inhibition of lipid transporters such as fatty acid binding protein 4 (FABP4) significantly reduces chemoresistance and metastasis in ovarian cancer." (PMID 36358644, 2022). "Under hypoxia, miR-409-3p was downregulated, and FABP4 functions as a downstream target of miR-409-3p in ovarian cancer." (PMID 35899119, 2022). "In a comparison of primary ovarian cancer and omental metastasis, FABP4 was found to be upregulated in omental metastatic ovarian cancer and is located at the interface between adipocytes and cancer cells." (PMID 33926551, 2021). "Elevated expression level of FABP4 is identified to be a key event in regulating adipocyte-induced lipid responses of co-cultured ovarian cancer cells, including β-oxidation, lipid peroxidation and reactive oxygen species (ROS) generation." (PMID 34888248, 2021). "On the other hand, recent work suggests that FABP4 increases tumor progression expressed in ovarian cancer cells and is regulated through miR‐409‐3p, triggering metastatic pathways and altering the metabolic state of cancer cells itself." (PMID 33016563, 2021). "In ovarian cancer microenvironment, IL-8, as an adipokine, can activate adipocytes along with the fatty acid-binding protein 4 (FABP4) to provide fatty acids, which provides energy to promote cancer cell omental metastasis." (PMID 34277625, 2021).
ovarian carcinoma (continued). "One of the proposed mechanisms that sustain this metabolic exchange is the increased expression of fatty acid-binding protein 4 (FABP4) in metastatic ovarian cancer cells at the interface with omental adipocytes." (PMID 34440886, 2021). "Omental adipocytes have also been shown to induce fatty acid binding protein 4 (FABP4) expression in ovarian cancer cells and promote metastasis and carboplatin drug resistance." (PMID 33498240, 2021). "In ovarian cancer, the rapid growth and metastatic colonization of cancer cells were suggested to be directly fueled by fatty acids delivered by fatty acid binding protein 4 (FABP4), also known as adipocyte FABP (A-FABP), from adipocytes." (PMID 33987528, 2021). "Taken together, these studies suggest that the adaptation of ovarian cancer cells to a lipid-rich environment is accompanied by an increased concentration of FABP4." (PMID 33809784, 2021). "In ovarian cancer, small molecule inhibition of FABP4 diminishes fatty acids transfer and lipid accumulation in cancer cells, impeding intraabdominal metastasis and growth." (PMID 34095111, 2021). "As a key mediator in adipocytes and cancer progression, FABP4 can be a worthy predictor of residual disease in ovarian cancer." (PMID 33194756, 2020). "In the latest research, knockdown of FABP4 in ovarian cancer cells resulted in the increasing level of 5-hydroxymethylcytosine, the downregulated expression of genes was associated with metastasis and the number of clone formation." (PMID 33194756, 2020). "Hypoxia decreases the expression of miR-409-3p, a regulator of FABP4 (fatty acid binding protein 4), which increases the metastatic potential of ovarian cancer cells." (PMID 32547948, 2020). "For example, FABP4 promotes metastasis of ovarian cancer to the omentum by facilitating the uptake of fatty acids from local adipocytes to cancer cells, which display increased lipid droplet formation and β-oxidation." (PMID 33352874, 2020). "In ovarian cancer, FABP4 promotes metastasis through direct transfer of lipids from adipocytes to invasive cancer cells for energy production." (PMID 33352874, 2020). "High expression of FABP4 contributes to the poor prognosis in Ovarian Carcinoma, nonsmall cell lung cancer, Pancreatic Ductal Adenocarcinomas, and hepatocellular carcinoma." (PMID 32685482, 2020). "FABP4 was highly expressed on the membrane of disseminated ovarian cancer cells at the adipocyte–cancer cell interface and mediated lipid accumulation in ovarian cancer cells." (PMID 31769430, 2019). "Inhibition of FABP4 led to reduced intracellular lipid accumulation and adipocyte-mediated invasion capability of ovarian cancer cells." (PMID 31769430, 2019). "In ovarian cancer, FABP4 was identified as a key regulator of metastasis and was associated with poorer prognosis." (PMID 31803141, 2019). "More recently, FABP4 was described by others as being critical to mediating the metastatic potential of ovarian cancer both in in vitro cell migration and invasion assays and in in vivo orthotopic mouse models." (PMID 31769430, 2019). "More importantly, in a xenograft ovarian cancer mouse model, the therapeutic delivery of siRNA targeting FABP4 in tumor vessels inhibited the tumor angiogenesis and peritoneal metastasis of ovarian cancer." (PMID 30568223, 2019). "FABP4 was determined to be upregulated in omental metastases compared to primary ovarian cancers and interestingly was restricted to tumor cells located at the interface of omental adipocytes." (PMID 30575815, 2019). "Conversely, ectopic expression of FABP4 in A2780-ip1 ovarian cancer cells led to increased migration (p < 0.05) and invasion of cancer cells (p < 0.01)." (PMID 30050129, 2018). "We used physiologically relevant concentrations of tamoxifen to determine its effect on FABP4 expression and function in ovarian cancer cells." (PMID 30050129, 2018). "Next, we examined the effect of FABP4 on tumor progression in orthotopic mouse models of ovarian cancer." (PMID 30050129, 2018).
ovarian carcinoma (continued). "To explore the effects of FABP4 on metabolic changes in human ovarian cancer tissues, we first analyzed previously published gene expression and metabolomics data of high grade serous ovarian carcinoma tissues." (PMID 30050129, 2018). "Here, we demonstrate that miR-409-3p acts as an effective tumor suppressor in ovarian cancer through its effects on FABP4." (PMID 30050129, 2018). "High expression of FABP4 can thus regulate various metabolites and protein pathways that can lead to aggressive metastasis of ovarian cancer." (PMID 30050129, 2018). "Downstream of FABP4, we observed that FABP4 can affect several metabolites as well as metastasis-related pathways in ovarian cancer." (PMID 30050129, 2018). "To investigate the functional role of FABP4 in ovarian cancer progression, we first knocked down FABP4 in HeyA8 MDR ovarian cancer cells (which have high FABP4 expression) using small interfering RNA (siRNA)." (PMID 30050129, 2018). "In summary, our study provides a new understanding of a previously unrecognized mechanism by which FABP4 leads to altered tumor metastasis patterns and a higher extent of disease in ovarian cancer." (PMID 30050129, 2018). "The effect was consistent when tested using a second siRNA sequence against FABP4, as well as another ovarian cancer cell line (Ovcar 5)." (PMID 30050129, 2018). "We also noted a positive correlation between the expression of FABP4 and the invasive capacity of ovarian cancer cell lines in vitro." (PMID 30050129, 2018). "In prostate and ovarian cancers, FABP4 acts as a key mediator between adipocytes and cancer progression." (PMID 30050129, 2018). "We also found that miR-409-3p regulates FABP4 in ovarian cancer cells and that hypoxia decreases miR-409-3p levels." (PMID 30050129, 2018). "Collectively, these findings demonstrate that FABP4 is functionally responsible for aggressive patterns of disease that likely contribute to poor prognosis in ovarian cancer." (PMID 30050129, 2018). "Here, the authors show miR-409-3p regulates FABP4 which can increase metastatic potential of ovarian cancer, and treatment with DOPC nanoliposomes containing either miR-409--3p mimic or FABP4 siRNA inhibits tumor progression in mice." (PMID 30050129, 2018). "We also transfected ovarian cancer cells (Ovcar 3) with anti-miR-409-3p and then examined FABP4 expression." (PMID 30050129, 2018). "Adipocytes are an important component of the tumor microenvironment, and promote ovarian cancer metastasis by the upregulation of FABP4 and IL-8." (PMID 29340091, 2017). "The elevated expression of FABP4 was reported in various types of cancer cells, and in cancer angiogenesis and metastatic proliferation in ovarian cancer, non-small cell lung cancer and breast cancer." (PMID 29340091, 2017). "Controversially, when adding a FABP4 inhibitor to a coculture of ovarian cancer cells and adipocytes, lipid accumulation in the cancer cells and adipocyte-mediated invasion were drastically reduced." (PMID 26959740, 2016). "Metastasized ovarian cancer cells showed upregulation of fatty acid binding protein 4 (FABP4), especially in the adipocyte–tumor interface and pharmacological inhibition of FABP4 substantially impaired ovarian metastases in mice." (PMID 24787299, 2014). "The underlying mechanism was suggested to be an up-regulation of fatty acid transporter gene, fatty acid binding protein 4 (FABP4), in the ovarian cancer cells positioned next to adipocytes to facilitate the transport of fatty acids." (PMID 24970804, 2014). "FABP4 was expressed primarily in endothelial cells in ovarian cancer, tumor cells colonizing the bone marrow, bone marrow adipocytes, and particularly strongly in tumor cells neighboring adipocyte-rich areas." (PMID 24240026, 2013). "FABP4 deficiency substantially impairs metastatic tumor growth in mice, indicating that FABP4 has a key role in ovarian cancer metastasis." (PMID 23109879, 2012).
ovarian carcinoma (continued). "FABP4 reduces apoptosis in ovarian cancer by enhancing mitochondrial β-oxidation." (PMID 40717587, 2025). "In addition, FABP4 increases the metastatic potential of ovarian cancer by regulating pathways related to ovarian cancer cell metabolism." (PMID 40814339, 2025). "For example, FABP4 enhances mitochondrial β-oxidation to reduce cisplatin-induced apoptosis in ovarian cancer, while FABP5 promotes chemoresistance in hepatocellular carcinoma through the HIF-1α pathway, and FABP6 enhances CRC resistance to oxaliplatin through KLF5-dependent transcription." (PMID 40717587, 2025). "Additionally, BMS309403, an inhibitor of FABP4, can increase the sensitivity of ovarian cancer to carboplatin." (PMID 40694956, 2025). "In addition, FABP4 also conferred resistance to doxorubicin and sorafenib, which is consistent with other findings showing the role of FABP4 in driving drug resistance in ovarian cancer." (PMID 41392988, 2025). "Proteomic and metabolomic analysis of carboplatin-resistant ovarian cancer cells identified the overexpression of FABP4, a lipid chaperone protein, as a crucial regulator of lipid responses in ovarian cancer cells that interact with adipocytes recruited by cancer cells during metastasis." (PMID 41065381, 2025). "FABP4 is lowly expressed in primary ovarian tumors, however, elevated FABP4 is observed in all omental metastases ovarian cancer samples; FABP4 is essential for ovarian cancer cells metastasizing to omentum via upregulation of lipid mobilization from omental adipocytes." (PMID 39125923, 2024). "FABP4 expression in ovarian cancer also promotes disease progression and chemoresistance." (PMID 38112643, 2024). "However, adipocyte‐induced FABP4 expression can promote ovarian cancer cell proliferation and metastasis both in vivo and in vitro." (PMID 37605299, 2023). "This suggests that FABP4 could be key in the ovarian cancer cell–adipocyte interaction, resulting in elevated lipid availability to favor metastasis." (PMID 36670988, 2023). "Moreover, primary human omental adipocytes induce FABP4 expression in ovarian cancer cells and promote metastasis and Carboplatin resistance in ovarian cancer cells." (PMID 36670988, 2023). "FABP4 modulates lipid metabolism of ovarian cancer cells by destroying tumor-infiltrating dendritic cells, thereby interfering with anti-tumor immunity, resulting in poor prognosis of ovarian cancer." (PMID 35216285, 2022). "FABP4 overexpression has been reported in many cancers including ovarian cancer." (PMID 35634242, 2022). "For example, fatty acid binding protein 4 (FABP4), a lipid chaperone protein, has been regarded as a critical regulator to adapt and colonize TME and is implicated and applied in ovarian cancer for the providence of fatty acids (FAs) from surrounding adipocytes to tumor cells." (PMID 36267966, 2022). "CD36 inhibition in ovarian cancer impairs adipocyte-driven FABP4 expression." (PMID 35899119, 2022). "FABP4 has the potential to predict the presence of residual disease in ovarian cancer." (PMID 35634242, 2022). "Targeting FABP4 can restrict ovarian cancer metastasis as a specific metabolic target." (PMID 36267966, 2022). "Inhibition of FABP4 effectively prevented early metastasis of ovarian cancer." (PMID 35198079, 2022). "Additionally, treatment with the FABP4 inhibitor suppressed ovarian cancer cell proliferation and omental colonization and increased the sensitivity of cancer cells to carboplatin." (PMID 35216285, 2022). "Indeed, it has been shown that inflammatory cytokines, such as IL17A, increase lipid uptake in ovarian cancer cells via the STAT3/FABP4 axis, leading to enhanced growth both in vitro and in vivo." (PMID 35565396, 2022). "The upregulation of FABP4 is closely associated with enhanced proliferation, migration, and epithelial‐mesenchymal transition (EMT) capacity of cancer cells such as breast, prostate, and ovarian cancer." (PMID 33931964, 2021).